RRM1 (ribonucleotide reductase catalytic subunit M1)
Diseases named in the same sentence as RRM1 in open-access papers (continued):
Sharing a sentence is not in itself a finding about the gene and the disease.
cancer (continued). "Since overexpression of RNR is one of the mechanisms underlying gemcitabine resistance in cancer cells, we attempted to study whether the combined treatment of afatinib and gemcitabine could affect the protein levels of RRM1 and RRM2." (PMID 29765556, 2018). "For instance, ribonucleoside-diphosphate reductase (RRM1), which encodes the regulatory subunit of ribonucleotide reductase, is hypothesized to be involved in the pathogenesis and development of carcinomas." (PMID 24926347, 2014). "Through this approach, we demonstrated thatthe translation of RRM1 is modulated by diphthamide and that the dysregulationof RRM1 translation contributes to the observed DNA replication stress.Our results provide a potential explanation for the association betweendiphthamide deficiency and cancer." (PMID 39463834, 2024). "The fact that Rrm1-Y285A acts as a dominant mutation contrasts with mutations that inactivate the exonuclease activity of Pol δ (Pold1e) and Pol ε (Polee), which are recessive mutants, and only Pold1e/e or Polee/e homozygous mice display mutator phenotypes and cancers." (PMID 39360631, 2024). "Consistent with the role of RR in DNA replication and repair, a high RRM1 expression is known to be associated with a poor response to the DNA-damaging platinum drugs and to the RRM1-targeting drug gemcitabine, and thus led to poor outcomes in these cancer patients." (PMID 31637211, 2019). "Its primary mechanism involves disrupting DNA synthesis by inhibiting Ribonucleotide Reductase M1 (RRM1), thereby hindering the proliferation of cancer cells." (PMID 40283935, 2025). "The splicing factorHNRNPA1, which contains two RNA recognition motifs (RRM1 and RRM2), has been linked to cancer progression by facilitating alternative splicing of PKM precursor mRNA exons." (PMID 37897508, 2024). "The present study has identified RRM1 as a cancer-promoting gene by promoting cell cycle progression in human ESCC." (PMID 38274374, 2024). "In The Cancer Genome Atlas database of human tumors (n = 11 125) there is a single patient with mutation at the conserved Y285 residue (TCGA-DDEI, RRM1-Y285C)." (PMID 39360631, 2024). "RRM1 plays a crucial role in DNA synthesis and repair, making it essential for the high proliferative activity of cancer cells." (PMID 39596229, 2024). "The response to clinical chemotherapy targeting RRM1 is closely related to the expression levels of RRM1 in cancer tissue." (PMID 38274374, 2024). "Our findings expand the understanding of RRM1’s biological function, providing new insights into its role in cancer biology and offering a potential target for cancer treatment." (PMID 39695160, 2024). "Of particular interest is the large subunit of RR, RRM1, which shows promise as a prognostic indicator for radiotherapy and chemotherapy in various cancers." (PMID 39695160, 2024). "The dysregulation of RRM1 and RRM2 has been implicated in cancer development, progression, and resistance to chemotherapy." (PMID 39682247, 2024). "Our study provides mechanisms by which AUR in combination with CHK1i inhibits cancer cell growth via regulation of cysteine oxidation of RRM1." (PMID 38821952, 2024). "Using the online GEPIA database analysis, we showed that high protein levels of RRM1 were observed in multiple types of human cancers." (PMID 35915092, 2022). "To investigate the relationship between TOP2A and RRM1 expression and cancer recurrence after treatment with pirarubicin or gemcitabine, we collected 85 NMIBC patient tissues obtained during TURBT." (PMID 35711974, 2022). "Based on The Cancer Genome Atlas (TCGA) enriched dataset, we analyzed the expression levels of RRM1 in human cancers." (PMID 35915092, 2022).
cancer (continued). "Pan-cancer expression profiling studies have revealed that the expression of RRM2 and RRM1 is upregulated in multiple types of cancers." (PMID 36230632, 2022). "Taken together, these data indicate that RRM1 inhibition combined with cisplatin can promote the occurrence of ferroptosis, thereby regulating the chemosensitivity in cancer cells." (PMID 35915092, 2022). "Here, we demonstrate for the first time a direct connection between RRM1 and radio-/chemotherapy-induced ferroptosis in cancer cells." (PMID 35915092, 2022). "Cell viability and colony formation in cancer cells were reduced when the radiation was combined with RRM1 knockdown." (PMID 35915092, 2022). "The new function of RRM1 as a negative regulator of radio-/chemotherapy-induced ferroptosis can be used to design new cancer treatments." (PMID 35915092, 2022). "Here, we report that targeting RRM1 promotes ferroptosis and affects sensitivity to radiation and chemotherapeutics in cancer cells." (PMID 35915092, 2022). "Our data provide strong support that RRM1 regulated the radiosensitivity of cancer cells by triggering ferroptosis." (PMID 35915092, 2022). "Overall, RRM1 was overexpressed in cancer tissues compared with normal tissues and was up-regulated upon radiation." (PMID 35915092, 2022). "We also found that RRM1 expression was mainly increased in the cytoplasm of cancer cells; similarly, immunofluorescence staining revealed that RRM1 expression was activated in the cytoplasm." (PMID 34111175, 2021). "The percentage of viable cells significantly decreased in both the RRM1 highly expressed cancer cells infected with Ad-shRRM1, three days after infection." (PMID 33921102, 2021). "In contrast, cancer cells free-floating in the medium and undergoing apoptosis increased DNA damage and cytoplasmic RRM1 activation was significantly abolished." (PMID 34111175, 2021). "There is already a collection of papers in the literature on the effects on cell proliferation and survival in cancer cells following inhibition of RRM1 expression and function." (PMID 34188151, 2021). "Ad-shRRM1 effectively knocked down RRM1 mRNA and protein expression in both RRM1 highly expressed cancer cell lines, in a time-dependent manner." (PMID 33921102, 2021). "RRM1 activation in response to gemcitabine exposure was induced mainly in the cytoplasm and cytoplasmic RRM1 activation was related to cancer cell viability." (PMID 34111175, 2021). "In contrast, although RRM1 expression was also found to be up-regulated in many types of cancers, its role in cancer development remains controversial." (PMID 31637211, 2019). "Gemcitabine was one of the famous RRM1 inhibitors and was approved clinically as first-line drug for anticancer therapy in various cancers." (PMID 31119182, 2019). "To further study associations of RRM1, RRM2, and RRM2B expression in different cancer types and TNM stages, we downloaded and analyzed the RNA-seq and clinicopathologic data of 31 types of cancer from TCGA." (PMID 31637211, 2019). "We collected cancer tissues from 81 patients to evaluate the mRNA expression of RRM1 by using liquid chip technology." (PMID 31340801, 2019). "RRM1’s role in cancer, however, is only discussed in terms of its involvement in DNA synthesis, and not in terms of telomere length regulation." (PMID 31822713, 2019). "In contrast, the expression of RRM2B in these cancers varied, and the correlations between the expression of RRM1 and RRM2B were weak and variably dependent on cancer type." (PMID 31637211, 2019). "RRM1, a target of five Food and Drug Administration (FDA) approved cancer drugs, were significantly associated with 13.8% (26/188) of differential modules." (PMID 29158875, 2017). "RRM1 has been previously spotted as a promising metabolic target in different cancer studies; however, a more systematic and unbiased analysis in MM was still lacking." (PMID 28878380, 2017).
cancer (continued). "It was found that the frequencies of RRM1 *151A>T A/A, A/T, and T/T genotypes among cancer cases were significantly different as those among controls (6.8%, 43.3%, and 49.9% vs. 7.0%, 41.9%, and 51.1%, P = 0.001)." (PMID 27335251, 2016). "For example, the aberrant regulation of ERCC1, TYMS, TUBB3, RRM1 and TOP2A is associated with the abnormal proliferation of cancer cells, according to the hallmarks of cancer that were proposed previously." (PMID 24926347, 2014). "Stratification analysis for expression of RRM1 at primary cancer and survival of GC patients in ZJU set." (PMID 23922955, 2013). "RRM1 is considered a therapeutic target for cancer treatment since it is involved in providing dNTPs for DNA synthesis." (PMID 23922955, 2013). "Furthermore, very recent studies linked high levels of RRM1 to the poor outcome of GBM patients and identified RRM1 as a promising target for drug combination therapy in this type of cancer." (PMID 38672281, 2024). "RRM1 expression is elevated in various cancer tissues compared to normal tissues." (PMID 39695160, 2024). "Our findings elucidate a previously unknown mechanism whereby RRM1 promotes HR-mediated DNA repair, presenting a potential therapeutic target for cancer treatment." (PMID 39695160, 2024). "Consequently, RRM1 has emerged as a prognostic marker in several cancer types, including non-small cell lung cancer, pancreatic cancer, breast cancer, and biliary tract cancer." (PMID 39695160, 2024). "DHFR and RRM1 are linked with sensitivity to therapeutics used in MPM, pemetrexed, and gemcitabine, respectively; however, they did not stratify by BAP1 status, implying more complex regulation of their expression in cancer." (PMID 36669126, 2023). "In most cancers, the mRNA expression of RRM1, RRM2, and RRM2B was generally increased." (PMID 36713030, 2023). "The knockdown of RRM1 increased the ROS levels induced by radiation in cancer cells." (PMID 35915092, 2022). "Researchers have suggested that the HER2 status may influence the effect of TOP2A on inhibitors on cancer cells, and a significant correlation exists between the expression of RRM1 and ERCC1 and response to chemotherapy." (PMID 35711974, 2022). "Next, we examined the effect of γ-ray on RRM1 expression in cancer cells." (PMID 35915092, 2022). "High RRM1-expression associates with gemcitabine-resistance in various cancers and RRM1 inhibition may provide novel cancer treatment approaches." (PMID 33921102, 2021). "The inhibitory effect of Ad-shRRM1 on RRM1 highly expressed cancer cells was evaluated." (PMID 33921102, 2021). "RNR catalyzes the rate-limiting step in dNTP synthesis and is a well-recognized target for cancer therapy; however, the biological role of RRM1, the main catalytic subunit of RNR, in SCLC remains unclear." (PMID 34188151, 2021). "Indeed, cytoplasmic RRM1 expression after gemcitabine exposure was activated mainly in attached and viable cancer cells." (PMID 34111175, 2021). "Notably, cytoplasmic RRM1 activation was observed only in cancer cells overcoming gemcitabine-induced DNA damage, implying that it is part of a cellular recovery process following exposure to the drug." (PMID 34111175, 2021). "Importantly, it is known that in humans, RRM1 is involved in regulation of cellular proliferation, migration and cancer progression, presumably due to its role in DNA replication." (PMID 31822713, 2019). "In addition, using publicly available genome-scale loss-of-function screens, a possible mechanism by which the inhibition of RRM1 is effective in cancer is established." (PMID 28878380, 2017).
cancer (continued). "The fact that cellular RRM2 is cell‐cycle‐regulated whereas RRM1 is constitutively expressed can perhaps explain this observation and leads to the prediction that a ∆F4L virus should replicate selectively in dividing cancer cells." (PMID 28289079, 2017). "In addition, using publicly available genome-scale loss-of-function screens, we establish a possible mechanism by which the inhibition of RRM1 is effective in cancer." (PMID 28878380, 2017). "Furthermore, PEG2000-hydrazone-C18 conjugate (PHC-2) micelles containing GemC18 have been shown to inhibit RRM1 expression and enhance the levels of dFdCTP in gemcitabine-resistant cancer cells." (PMID 29144412, 2017). "However, the frequencies of RRM1 ‐756T>C and RRM1 ‐269C>A genotypes were almost the same as those among in cancer cases and controls (P = 0.11 and P = 0.19)." (PMID 27335251, 2016). "RRM1 is one of the three known human ribonucleotide reductase with the functions of regulating the cancer cell proliferation via mediating DNA synthesis and repair, and detection of the expression of RRM1 in GC tissues by IHC has been identified to have prognostic significance in patients with GC." (PMID 26472090, 2015). "Therefore, extensively investigating the roles of RRM1 would be helpful in developing novel RNR inhibitors for treating cancer specifically." (PMID 23922955, 2013). "Moreover, aberrant RRM1expression has been implicated in various human cancers and is considereda potential therapeutic target for cancer treatment.5−7 Therefore, understanding the intricate interplay between RRM1 andDNA replication stress is crucial to unraveling carcinogenesis mechanisms." (PMID 39463834, 2024). "RRM1 might play different tissue-specific functions depending on cancer types." (PMID 36175487, 2022). "In our opinion, this information is certainly relevant and could open new avenues for the development of tools for personalized medicine in cancer, since the expression of partner genes of RRM1 can be used as a signature to predict the response to RRM1 inhibition." (PMID 28878380, 2017). "Loss of MGMT and RRM1 was common among the four cohorts and may be predictive of response to cytotoxic therapies not currently being used to treat these cancer types." (PMID 28556593, 2017). "However, in gemcitabine-resistant MIA PaCa-2 cancer cells, knockdown of RRM1 could completely overcome the gemcitabine resistance." (PMID 29144412, 2017). "Furthermore, our results in budding yeast suggest that telomerase-positive cancer cells may be more sensitive to RRM1/RRM2 inhibition than ALT-positive cancer cells." (PMID 29069086, 2017). "The roles of RRM1 in different cancers are still largely unknown." (PMID 23922955, 2013). "Different treatments also could alter the roles of RRM1 in cancers." (PMID 23922955, 2013). "The present study aimed to understand the role of RRM1 on the malignant proliferation process, and further clarify the molecular mechanism in ESCC development, which would be helpful in anti-cancer therapy of ESCC patients." (PMID 38274374, 2024). "Given their role in DNA synthesis and repair, RRM1 and RRM2 are attractive targets for novel cancer therapies." (PMID 39682247, 2024). "Multiple types of cancer, including Ewing sarcoma tumors, are sensitive to RNR inhibitors or a reduction in the levels of either the RRM1 or RRM2 subunits of RNR." (PMID 37599787, 2023). "RRM1 and RRM2 are good predictors to distinguish cancer tissue from normal liver tissue based on TCGA cohort." (PMID 36713030, 2023). "Positivity of protein marker expression for all cancers combined was: ERCC1 20.9%, MGMT 55.4%, RRM1 19.9%, TOPO1 58.7%, TOP2A 75.8%, TS 34.0% and TUBB3 56.8%." (PMID 31479512, 2020). "We found that the mRNA expression levels of RRM1, RRM2, and RRM2B ranked in the top 10% of the up-regulated DEGs in 24.0% (86 of 358), 38.3% (136 of 355), and 10.5% (22 of 209) of the identified cancer studies, respectively." (PMID 31637211, 2019).
cancer (continued). "Using the Spearman's correlation coefficient analysis, the consistent positive correlations were observed between RRM1 and RRM2 expression in all 31 types of cancer." (PMID 31637211, 2019). "In contrast, RRM1, RRM2, and RRM2B were ranked in the top 10% of the down-regulated DEGs in only 8.4% (30 of 358), 4.5% (16 of 355), and 4.8% (10 of 209) of the cancer studies, respectively." (PMID 31637211, 2019). "The expression of three RR genes, especially RRM1 and RRM2, increased significantly across common types of cancers." (PMID 31637211, 2019). "The RRM1 of PTBP1 is therefore crucial for this interaction in mediating biological functions and cancer progression." (PMID 31729427, 2019). "Western blots showed a general elevation in the levels of cellular RRM1, RRM2, and TK1 in cancer cell lines compared to normal cells." (PMID 28289079, 2017). "One of the major targets of gemcitabine is RRM1 and RRM2, which ensure sufficient supply of dNTP pool for DNA synthesis of proliferating cancer cells." (PMID 26894857, 2016). "The goal, therefore, is to discover truly selective RRM1 or RRM2 compounds for use as monotherapy and in combination with CHK1 inhibitors or chemotherapy for the treatment of cancer." (PMID 25375241, 2014). "Increasing evidence has demonstrated that the expression levels of ERCC1, TYMS, TUBB3, RRM1 and TOP2A are closely correlated with the pathogenesis of carcinomas." (PMID 24926347, 2014). "Therefore, RRM1 might potentially lead to better outcomes of some cancer patients." (PMID 23922955, 2013). "Unlike the Rrm1+/Y285A mice, heterozygous mice carrying mutation in MMR genes are indistinguishable from their WT controls with respect to survival and cancer phenotypes in most cases." (PMID 39360631, 2024). "In summary, our findings offer new mechanistic insight into the regulation of RRM1 and indicate that the lack of RRM1 exacerbates ferroptosis of cancer cells upon DNA damage, and targeting RRM1 improves radio-/chemotherapy." (PMID 35915092, 2022). "In contrast, cancer cells lacking cytoplasmic RRM1 activation were confirmed to show severe DNA damage." (PMID 34111175, 2021). "This showed that RRM1 was overexpressed in cancer cells but not in adjacent normal pancreatic tissues." (PMID 34111175, 2021). "RRM1 and RRM2 are often overexpressed in cancer tissues including lung." (PMID 29765556, 2018). "The reduction of the dNTP pool and growth retardation could be seen in AGS and NCI-N87 cells after RRM1 siRNA treatment, which is consistent with the fact that the Ras/Raf/MAPK signaling pathway is related to cancer cell growth and metastasis." (PMID 23922955, 2013). "And there are also some studies explain why RRM1 and RRM2 play opposite roles in cancer outcomes." (PMID 23922955, 2013). "We studied 39 consecutive NSCLC patients and measured the expression of six molecular markers (MDR-1, LRP, RRM-1, EGFR, ERCC-1, BRCA-1) in their primary tumors and metastatic lymph nodes and four well-known serum markers for cancer (NSE, CEA, CA-125, CYFRA 21-1)." (PMID 22890830, 2012). "RRM1 has been suggested to have other biological roles besides forming RNR holoenzymes to convert NDP to dNDP, which could partially explain the low efficacy of RNR inhibitors in cancer treatment." (PMID 23922955, 2013).